PTK2B (protein tyrosine kinase 2 beta)
Description:
Non-receptor protein-tyrosine kinase that regulates reorganization of the actin cytoskeleton, cell polarization, cell migration, adhesion, spreading and bone remodeling. Plays a role in the regulation of the humoral immune response, and is required for normal levels of marginal B-cells in the spleen and normal migration of splenic B-cells. Required for normal macrophage polarization and migration towards sites of inflammation. Regulates cytoskeleton rearrangement and cell spreading in T-cells, and contributes to the regulation of T-cell responses. Promotes osteoclastic bone resorption; this requires both PTK2B/PYK2 and SRC. May inhibit differentiation and activity of osteoprogenitor cells. Functions in signaling downstream of integrin and collagen receptors, immune receptors, G protein-coupled receptors (GPCR), cytokine, chemokine and growth factor receptors, and mediates responses to cellular stress. Forms multisubunit signaling complexes with SRC and SRC family members upon activation; this leads to the phosphorylation of additional tyrosine residues, creating binding sites for scaffold proteins, effectors and substrates. Regulates numerous signaling pathways. Promotes activation of phosphatidylinositol 3-kinase and of the AKT1 signaling cascade. Promotes activation of NOS3. Regulates production of the cellular messenger cGMP. Promotes activation of the MAP kinase signaling cascade, including activation of MAPK1/ERK2, MAPK3/ERK1 and MAPK8/JNK1. Promotes activation of Rho family GTPases, such as RHOA and RAC1. Acts as a scaffold, binding to both PDPK1 and SRC, thereby allowing SRC to phosphorylate PDPK1 at 'Tyr-9, 'Tyr-373', and 'Tyr-376'. Promotes phosphorylation of NMDA receptors by SRC family members, and thereby contributes to the regulation of NMDA receptor ion channel activity and intracellular Ca(2+) levels. May also regulate potassium ion transport by phosphorylation of potassium channel subunits. Phosphorylates SRC; this increases SRC kinase activity. Phosphorylates ASAP1, NPHP1, KCNA2 and SHC1. Promotes phosphorylation of ASAP2, RHOU and PXN; this requires both SRC and PTK2/PYK2.
Synonyms: CADTK; CAKB; RAFTK; FAK2; PYK2; PTK; FADK2; PKB
Tractability: Small molecule: a drug acting on it is in phase 2 or 3 trials; a structure with a bound ligand is known; a high-quality ligand is known; it has a high-quality binding pocket; it belongs to a druggable protein family. Antibody: UniProt places it where antibodies can reach, with medium confidence; its Gene Ontology location is reachable by antibodies, with medium confidence; the Human Protein Atlas places it where antibodies can reach. PROTAC: it is named in the literature on targeted protein degradation; ubiquitination databases record sites on it; its protein half-life has been measured; a small molecule that binds it is known.
Target class: Enzyme; TK protein kinase group; Tyrosine protein kinase Fak family; Kinase; Protein Kinase
Chemical probes: DEFACTINIB (high quality)
Gene: Protein-coding gene on chromosome 8 (27,311,456 to 27,459,392, forward strand). Ensembl gene ENSG00000120899.
Subcellular location: Cytoplasm; Cytoplasm, perinuclear region; Cell membrane; Cell junction, focal adhesion; Cell projection, lamellipodium; Cytoplasm, cell cortex; Nucleus
Subcellular location (Human Protein Atlas): Cytosol; Plasma membrane
Pathways (Reactome):
Signal Transduction: RHOU GTPase cycle; VEGFA-VEGFR2 Pathway
Cell-Cell communication: Signal regulatory protein family interactions
Immune System: Interleukin-2 signaling
Gene Ontology:
Molecular function: non-membrane spanning protein tyrosine kinase activity; protein binding; protein tyrosine kinase activity; calcium/calmodulin-dependent protein kinase activity; ionotropic glutamate receptor binding; neurotransmitter receptor regulator activity; signaling receptor activator activity; ATP binding; protein kinase activity
Biological process: activation of Janus kinase activity; cell surface receptor signaling pathway; cellular response to retinoic acid; endothelin receptor signaling pathway; integrin-mediated signaling pathway; negative regulation of apoptotic process; negative regulation of cell population proliferation; negative regulation of myeloid cell differentiation; negative regulation of potassium ion transport; peptidyl-tyrosine autophosphorylation; peptidyl-tyrosine phosphorylation; positive regulation of actin filament polymerization; positive regulation of cell migration; positive regulation of cell population proliferation; positive regulation of cell-matrix adhesion; positive regulation of endothelial cell migration; positive regulation of ERK1 and ERK2 cascade; positive regulation of JNK cascade; positive regulation of neuron projection development; positive regulation of protein kinase activity; regulation of cell adhesion; regulation of cell shape; regulation of ubiquitin-dependent protein catabolic process; tumor necrosis factor-mediated signaling pathway; vascular endothelial growth factor receptor signaling pathway; and 31 more
Cellular component: cytosol; focal adhesion; lamellipodium; nucleus; perinuclear region of cytoplasm; plasma membrane; apical dendrite; cell body; cytoplasm; dendrite; growth cone; neuronal cell body; NMDA selective glutamate receptor complex; postsynaptic density; cell cortex; cell junction; glutamatergic synapse; postsynaptic density, intracellular component; presynapse
Genetic constraint (gnomAD): Loss-of-function variants: 67 observed, 146.07 expected, observed/expected ratio (o/e) 0.46, 90% interval 0.38 to 0.56. The upper end of that interval is the gene's LOEUF score, 0.56, which puts it in group 2 of 6, group 1 being the genes least tolerant of losing a copy. Missense variants: 1,092 observed, 1,364.4 expected, observed/expected ratio (o/e) 0.8, 90% interval 0.76 to 0.84. Synonymous variants: 515 observed, 522.35 expected, observed/expected ratio (o/e) 0.99, 90% interval 0.92 to 1.06.
Homologues: Orthologues: chimpanzee PTK2B (99% identical), macaque PTK2B (98% identical), pig PTK2B (96% identical), dog PTK2B (96% identical), rabbit PTK2B (96% identical), guinea pig PTK2B (95% identical), mouse Ptk2b (95% identical), rat Ptk2b (95% identical), tropical clawed frog ptk2b (76% identical), zebrafish ptk2bb (59% identical). Paralogues in human: PTK2 (47% identical), ABL2 (19% identical), ABL1 (19% identical), SRC (16% identical), FRK (16% identical), FYN (16% identical), YES1 (16% identical), BLK (16% identical), HCK (16% identical), SYK (16% identical), TNK2 (16% identical), ZAP70 (15% identical), and 20 more.
Diseases named in the same sentence as PTK2B in open-access papers:
PTK2B is named in the same sentence as 187 diseases in open-access papers, as found by Europe PMC text mining. Sharing a sentence is not in itself a finding about the gene and the disease. The quoted sentences say what the papers report.
breast cancer (56 papers, 2007 to 2025). A primary or metastatic malignant neoplasm involving the breast. "In BL1, the enriched kinases, such as LCK and PTK2B, were associated with tumorigenesis, as well as invasion of breast cancer, whereas ZAP70 was reported to be related to drug resistance in TNBC." (PMID 36672350, 2023). "In breast cancer, PTK2B overexpression is associated with tumor growth and recurrence, playing a role in countering BMP, a protein that controls cell growth and differentiation." (PMID 37622116, 2023). "The relatively rare mutations in PTK2B and their distribution are consistent with its activity as a secondary driver with tumor suppressor activity, as described for breast cancer, or as an oncogene, as described for hepatocellular carcinoma." (PMID 31671564, 2019). "In this study, we applied genetic approaches to ablate the PYK2 gene (PTK2B) either in breast cancer cells using the CRISPR/Cas9 technology, in the TME (total knockout mice), or selectively in macrophages (Cx3cr1‐Cretg/wt/PYK2f/f mice)." (PMID 35092356, 2022). "The combination of the target fishing approach with breast-cancer-associated genes enabled the identification of two possible targets (EGFR and PTK2B) that could serve as multi-target ligands." (PMID 40872597, 2025). "To demonstrate its clinical relevance, we assessed the correlation between PYK2 expression (PTK2B gene) and macrophage markers (CD68, CD163) in human breast cancer datasets." (PMID 35092356, 2022). "The primary tumor was also tested through IHC, NP‐C8018‐7840 significantly inhibited the phosphorylation of PTK2B at Tyr402, PTK at Tyr397, and SRC at Tyr416 of the breast cancer primary site, but had little impact on total‐PTK2B, total‐PTK, and total‐SRC." (PMID 36285700, 2022). "Inhibition of NRTKs in the PTK2B-Src-ABL2-cortactin cascade, in particular of ABL2, effectively inhibits the invadopodia-mediated invasiveness and metastasis of human breast cancer cells in a mouse tumor model." (PMID 35008569, 2021). "Proline-rich tyrosine kinase 2 (PTK2B/PYK2) is a focal adhesion tyrosine kinase that shares structural and sequence homology with focal adhesion kinase (FAK) and has also been shown to promote cell migration and invasion in a variety of cancers, such as breast cancer." (PMID 36056084, 2022).
glioma (42 papers, 2008 to 2025). A benign or malignant brain and spinal cord tumor that arises from glial cells (astrocytes, oligodendrocytes, ependymal cells). "Treatment with microglia-conditioned media activates the protein tyrosine kinase 2 beta (Pyk2) signaling pathway in glioma cells." (PMID 28670569, 2017).
glioblastoma (26 papers, 2010 to 2025). The most malignant astrocytic tumor (WHO grade IV). "Similarly, PTEN deficiency in glioblastoma cells activates Yap1, which upregulates Lysyl Oxidase (LOX) expression, attracting macrophages to the tumor microenvironment via the β1 integrin-PYK2 (protein tyrosine kinase 2-beta) pathway." (PMID 40057606, 2025). "Kaplan–Meier analysis of 619 glioblastoma cases from the glioblastoma tumor RNA-Sequence dataset identified a negative association between levels of gene expression of PTK2 and PTK2B and overall survival." (PMID 37686276, 2023).
Alzheimer disease (23 papers, 2014 to 2025). A progressive, neurodegenerative disease characterized by loss of function and death of nerve cells in several areas of the brain leading to loss of cognitive function such as memory and language. "PTK2B has been identified as a risk factor for Alzheimer’s disease by multiple studies, and the mechanism of some susceptibility alleles has been attributed to splicing alterations." (PMID 40593860, 2025). "PTK2B has also been reported in memory formation and corresponding protein variants can trigger cognitive dysfunction and higher prevalence of Alzheimer's disease." (PMID 36911092, 2023). "The PTK2B locus encoding the Pyk2 protein is one of the few validated GWAS risk factors for late-onset Alzheimer’s disease expressed primarily in neurons." (PMID 35501917, 2022). "We detect an association between an increase in PTK2B expression and Alzheimer’s disease specifically in monocytes and blood, suggesting that the association in Alzheimer’s disease is specific to blood." (PMID 33959712, 2021). "We show that there is an Alzheimer’s disease-associated increase in expression of PTK2B in CD14+ monocytes (Fairfax), whole blood and peripheral blood (GTEx7 and YFS, respectively)." (PMID 33959712, 2021). "Genetic variation at the PTK2B locus encoding the protein Pyk2 influences Alzheimer’s disease risk." (PMID 35501917, 2022). "Pyk2 gene, PTK2B, is associated with the risk for late-onset Alzheimer’s disease." (PMID 34690733, 2021). "The 5th ranked putative target, PTK2B, is a key gene in the mediation of synaptic dysfunction induced by amyloid- β in Alzheimer’s disease." (PMID 33941241, 2021). "LACTB2 and PLIN2 had novel significant associations with Alzheimer’s disease and BIN1, PTK2B, SPI1, MS4A4A, MS4A6E, APOE and PVR are in known Alzheimer’s disease risk loci from GWAS." (PMID 33959712, 2021). "PTK2B has been widely studied since it was identified as a novel Alzheimer’s disease (AD) candidate gene in a large meta-analysis of AD GWAS." (PMID 26931105, 2016). "Additionally, protein tyrosine kinase 2 beta (PTK2B), clusterin, and cholinergic receptor nicotinic alpha 2 (CHRNA2) genes are considered genetic risk factors for late-onset Alzheimer’s disease." (PMID 41007636, 2025). "Protein tyrosine kinase 2β (PTK2B)/clusterin (CLU) and membrane-spanning 4A (MS4A) were significantly associated with the onset of all-cause dementia, whereas aph-1 homolog B (APH1B) was specifically linked to Alzheimer's disease." (PMID 40949174, 2025). "While PTK2B has been studies extensively in Alzheimer’s disease, its role in CAD remains unexplored, suggesting that it could be a new biomarker for CAD treatment and prevention." (PMID 40857258, 2025). "Although we see an Alzheimer’s disease-associated decrease in expression of PTK2B in LPS-induced monocytes (24 h), this is not replicated when using the Marioni summary statistics and we do not see an association in IFN-induced monocytes." (PMID 33959712, 2021). "The FN1+ MG subcluster exhibits high expression of the Alzheimer’s disease risk genes ABI3, CD33, and PTK2B, suggesting that this component of CSF microglia-like cells could emerge from a specific myeloid cell response to protein aggregates accumulating in the parenchyma during neurodegeneration." (PMID 39744938, 2025). "While PTK2B, IL8 and HLA-DRB5 are clearly involved in Alzheimer pathology, there are controversial studies about the involvement of PICALM in Alzheimers disease." (PMID 25765079, 2015). "In this article, we first introduce the pathological features of Alzheimer's disease, and describe recent data linking NEDD9, CASS4, and PTK2B to this syndrome." (PMID 25594051, 2014). "We have shown an association between changes in gene expression in naïve and induced CD14+ monocytes and Alzheimer’s disease in seven genes in known Alzheimer’s disease loci, three of which (PVR, PTK2B and MS4A6E) replicated in TWAS using independent summary statistics." (PMID 33959712, 2021).
Alzheimer disease (continued). "We applied our computational framework to prioritize novel putative target genes for Alzheimer’s disease and successfully identified key genes that may serve as novel therapeutic targets (e.g., DLG4, EGFR, RAC1, SYK, PTK2B, SOCS1)." (PMID 33941241, 2021).
hepatocellular carcinoma (21 papers, 2007 to 2025). A malignant tumor that arises from hepatocytes. "In this sense, previous studies have shown that downregulation of miR-517a and miR-517c contribute to the development of hepatocellular carcinoma through post-transcriptional regulation of Pyk2 (protein tyrosine kinase 2 beta), which is associated with blockade of the G2/M transition." (PMID 37887350, 2023).
prostate carcinoma (19 papers, 2010 to 2025). A carcinoma that arises from epithelial cells of the prostate gland. "Recent studies have found that DSF/Cu complex induces the death of prostate cancer cells through the activation of CLC3 chloride channel with the participation of PTK2B." (PMID 41166024, 2025). "In prostate cancer cells, OR51E2 activation results in an activation of protein tyrosine kinase 2 beta (Pyk2), which in turn leads to the phosphorylation of p38 mitogen-activated protein kinases." (PMID 29249973, 2017).
ovarian carcinoma (16 papers, 2011 to 2025). A malignant neoplasm originating from the surface ovarian epithelium. "Defactinib has recently been granted breakthrough therapy designation by the FDA for the treatment of ovarian cancer, which thus could facilitate a timely investigation of the benefits of PTK2B/FAK inhibition also in FLT3-ITD mutated AML patients, based on the results of this study." (PMID 36056084, 2022).
lung carcinoma (14 papers, 2008 to 2024). "Likewise, prescription of crizotinib and merelotinib in NSCLC patients underscores the importance of PTK2B in the pathogenesis of lung cancer." (PMID 29062084, 2017). "In addition to lung cancer, PTK2B also plays different roles in other types of cancers." (PMID 37622116, 2023). "Co-expression network construct indicated that some of the mostly connected mRNAs and TFs were previously reported to be dysregulated in lung cancer, including SOX2, FOXF1, PTK2B, XRCC2, AML-1a (RUNX1), GATA-2 and MZF1." (PMID 26159226, 2015). "In the present study, some of the mostly connected mRNAs were already reported to be correlated with lung cancer, including SOX2, FOXF1, PTK2B and VHL." (PMID 26159226, 2015).
melanoma (12 papers, 2008 to 2023). A malignant, usually aggressive tumor composed of atypical, neoplastic melanocytes. "Mutation analysis of protein tyrosine kinases identified some recurrent mutations in ERBB4 (19% of melanomas) and Fms related Tyrosine Kinase 1 (FLT1) and Protein Tyrosine Kinase 2 Beta (PTK2B) (10% of melanomas)." (PMID 29156643, 2017).
asthma (8 papers, 2011 to 2024). "PTK2B is required for neutrophil degranulation and inhibition of PTK2B blocks inflammation in murine models of acute lung injury and asthma." (PMID 25594051, 2014).
leukemia (8 papers, 2018 to 2025). A malignant (clonal) hematologic disorder, involving hematopoietic stem cells and characterized by the presence of primitive or atypical myeloid or lymphoid cells in the bone marrow and the blood. "This led to the hypothesis that FLT3-ITD inhibition might result in leukemia cell detachment from the bone marrow niche through PTK2B inhibition." (PMID 36056084, 2022). "In line with the importance of CAMs in drug-resistance and the interplay of leukemia cells with the bone marrow niche, resistant cells showed significantly altered migration and adhesion properties, and both LPXN and PTK2B were upregulated in LSCs of FLT3-mutated patients." (PMID 36056084, 2022). "We anticipate that pharmacological inhibitors of the identified targets, e.g. PAK2 and PTK2B/PYK2, may have great clinical potential as therapy for lymphoma and leukemia patients." (PMID 35440579, 2022).
depression (7 papers, 2012 to 2025). "Here we propose for the first time a potential mechanism that could explain the human association of PTK2B to the risk to develop depression after chronic stress." (PMID 30664624, 2019). "Both PTK2B and GZMK have been linked to brain physiology and depression through animal models." (PMID 22649524, 2012).
multiple myeloma (7 papers, 2016 to 2021). "Ptk2b specifically induces cell death and reduces clonogenic growth in myeloma cell lines and multiple myeloma stem cells." (PMID 29348887, 2017). "Furthermore, Ptk2b inhibition attenuates multiple myeloma progression." (PMID 29348887, 2017).
non-small cell lung carcinoma (7 papers, 2010 to 2024). A group of at least three distinct histological types of lung cancer, including non-small cell squamous cell carcinoma, adenocarcinoma, and large cell carcinoma. "In non-small cell lung cancer (NSCLC), PTK2B activation can cause many cellular biological processes, including proliferation, differentiation, migration, invasion, and apoptosis." (PMID 37622116, 2023).